TRIM33 (tripartite motif containing 33)
Diseases named in the same sentence as TRIM33 in open-access papers (continued):
Sharing a sentence is not in itself a finding about the gene and the disease.
cancer (continued). "TRIM24 and TRIM28 are generally positively associated, while TRIM33 and TRIM66 are mostly negatively associated with cancer stemness in solid tumors." (PMID 33810347, 2021). "In contrast to the other TIF1 family members, TRIM33 has predominantly been identified as a tumor suppressor, although several studies imply its engagement in promoting cancer progression." (PMID 33810347, 2021). "We observed that TRIM33 is downregulated not only in KIRC but also in many cancers such as GBM, KIRP, THYM, and UCEC." (PMID 32908919, 2020). "Analysis of human cancer cell lines and patient data revealed that reduced TRIM33 expression correlates with increased genomic rearrangements, further indicating that TRIM33 regulates chromosomal stability." (PMID 32731534, 2020). "Cancer suppressive drugs targeting TRIM33 have been tested in various cancer mouse models and have shown good results." (PMID 32908919, 2020). "In fact, TRIM33 has been suggested as a potential prognostic marker and therapeutic target for cancer patients." (PMID 32908919, 2020). "TRIM33 is a tumor suppressor that can inhibit tumor cell progression and tumorigenesis by different mechanisms in several cancers, including HCC." (PMID 31153371, 2019). "Previous studies have showed that miR-629-5p involves in tumor progression via down-regulating FOXO3, Testis-specific Y-like protein 5, or TRIM33 in different types of cancer." (PMID 30042169, 2018). "Collectively, these findings suggest that B lymphoid cells are uniquely sensitive to TRIM33 inhibition, thus implicating TRIM33 as a lineage dependency in cancers of B cell origin." (PMID 25919951, 2015). "In addition, established cancer genes like Lmo2, RhoH, Trim33, Mll, and Hspca are candidate target genes of less frequently mutated CISs, indicating that lower ranked CISs (carrying 4–5 insertions) may represent bona fide cancer genes." (PMID 18485879, 2008). "Binding of ncRNAs to TRIM33 intron 1 could indeed trigger intron retention, which has been described in the context of cancer and other diseases because it alters transcriptome plasticity and the expression of oncosuppressor genes." (PMID 38929849, 2024). "Due to the apparent context-dependent nature of TRIM33 and its widespread expression across tissues, TRIM33-directed therapy may require targeting of cancer cells to avoid toxicity to normal tissues." (PMID 38473207, 2024). "Cancer studies have shown that TRIM33 acts as an oncogene in the development of several tumors." (PMID 39389957, 2024). "TRIM33 has attracted attention due to its undeniable role in various cancers." (PMID 39062881, 2024). "TRIM33, a member of the E3 ubiquitin ligase family, is involved in a wide range of biological processes, including DNA repair, cell differentiation, inflammation, and cancer." (PMID 39389957, 2024). "Furthermore, low TRIM33 expression across several cancer types correlates with an increased rate of genomic rearrangements, suggesting a role for TRIM33 in regulating genomic stability." (PMID 38627415, 2024). "For instance, TRIM33 binds to DHX33 and boosts its ubiquitylation at Lys63, resulting in the activation of the NLRP3 inflammasome; TRIM33 targets β‐catenin and mediates its ubiquitylation and degradation to restrain the proliferation of various types of cancer cells." (PMID 34101965, 2021). "However, knockdown of TRIM33 can increase the growth rate of cancer cells in line with its tumour suppressor function." (PMID 32731534, 2020). "Multiple mouse models of cancer have demonstrated a role for Trim33 as a tumour suppressor." (PMID 26624618, 2015). "Taken together, these findings indicate Trim33 can be considered a corepressor of transcription that functions by ubiquitinating DNA-binding cofactors and that it has important roles in development and cancer." (PMID 26624618, 2015). "Notably, TRIM33 is controversial regarding its function involved with cancer progression." (PMID 40723250, 2025).
cancer (continued). "Cancer cells in the very early phase of malignant transformation may express a variety of lncRNA transcripts, some of which overlap with the nucleotide sequence of TRIM33." (PMID 38929849, 2024). "However, evidence for the mechanism of intron retention of the TRIM33 gene as pathogenic in cancer and DM is lacking." (PMID 38929849, 2024). "However, the data clarifying the role of TRIM33 in cancer stemness are still missing." (PMID 36674511, 2023). "Collectively, our data identify a role for the Trim33-E2f4-Recql axis in the cellular response to oncogene- and drug-induced replicative stress and may provide important insights for the development of targeted cancer therapies." (PMID 37612308, 2023). "Additionally, where reduced expression is observed in cancers, for example TRIM33, this could potentially be utilised as a biomarker for predicting prognosis or cancer stage, or to stratify patients who may respond to DNA damaging agents or BETi." (PMID 32731534, 2020). "Therefore, the aim of this work was to investigate possible interactions between the TRIM33 gene and human ncRNAs based on sequence complementarities and RNA interactome analysis in silico and to correlate these results with the panorama of existing data on ncRNA profiling in cancer and DM." (PMID 38929849, 2024). "Interestingly, even in the same type of cancer, TRIM33 may be carcinogenic or tumor-suppressive." (PMID 39389957, 2024). "Interestingly, some other members of the TRIM family are involved in cancer development, some of which are due to chromosomal translocations like TRIM24/TIF1a, TRIM27/RFP, and TRIM33/TIF1g, whose RBCC motifs play a critical role in cell transformation." (PMID 38611029, 2024). "Therefore, it is not surprising that TRIM33 expression negatively correlates with cancer stemness, at least in several tumor types." (PMID 33810347, 2021). "These defects were initially not retained in our filtering, because known cancer genes (NRAS, BCL10, TRIM33, RBM15) are also included in the same deletion and the minimal mutational frequency requirement was not satisfied." (PMID 28147343, 2017).
tumor (88 papers, 2009 to 2026). "For example, retinoblastoma-associated protein (RB1), a predicted substrate of TRIM33, is a key tumor suppressor to regulate the G1/S transition of the cell cycle." (PMID 39062881, 2024). "Another report associated tumor TRIM33 overexpression with a poor prognosis in relation to the TGF-β pathway." (PMID 38473207, 2024). "Suppression of these surveillance mechanisms in Trim33-deficient cells leads to overt DNA damage and delays tumor development, possibly both by cell-intrinsic effects (increased tumor cell death) and via activation of immune responses." (PMID 37612308, 2023). "Trim33-deficient tumors had strongly elevated levels of pH2AX, suggesting that DNA damage upon acute Myc overexpression delays tumor development in the liver." (PMID 37612308, 2023). "We report, for the first time, a significant depletion of TRIM33-associated transcriptome profiles with stemness-related genes in most TCGA tumor types." (PMID 33810347, 2021). "As for TRIM33, the associated transcription profiles were significantly depleted, with stem cell markers in 19 tumor types and the NES values for Wong ESC core signature ranging from −4.16 (ESCA) to −2.01 (PRAD)." (PMID 33810347, 2021). "It is plausible that the overexpression of TRIM33 could be an attempt to curb the production of lncRNAs associated with tumor progression." (PMID 38929849, 2024). "In vivo studies further demonstrated this, with TRIM33 loss driving tumour progression." (PMID 32731534, 2020). "KEGG enrichment analysis showed that the potential target protein of TRIM33 affected a variety of signal pathways related to tumor metabolism, such as pyruvate production and TCA cycle related to glucose metabolism." (PMID 39389957, 2024). "Clinically, reduced TRIM33 expression in tumors correlates with higher genomic rearrangements, indicating its role in promoting chromosomal stability and tumor suppression." (PMID 39160596, 2024). "Here, our study reveals that in LSCC, TRIM33 also functions as a tumor suppressor by inhibiting the cell cycle, thus addressing a gap in elucidating the function of TRIM33 in LSCC." (PMID 39062881, 2024). "This degradation of nuclear β-catenin is essential for the role of TRIM33 in suppressing tumor cell proliferation and brain tumor development through Wnt/β-catenin signaling." (PMID 39160596, 2024). "In this analysis, the TRIM33 gene appears to have sequence complementarity with human ncRNA genes, mainly lncRNAs, some of which play a critical role in tumor development and progression." (PMID 38929849, 2024). "In B cell lymphoblastic leukemia, pancreatic cancer, cervical cancer, and prostate cancer, TRIM33 can promote tumor growth and prevent tumor cell apoptosis." (PMID 39389957, 2024). "We then assessed the expression of Trim33 and pH2AX using immunohistochemistry on tissue sections of tumor-bearing livers." (PMID 37612308, 2023). "Trim33-deficient tumors had a significantly increased number of CD3-positive cells, suggesting that loss of Trim33 can promote tumor infiltration by T cells, contributing to delayed tumor development." (PMID 37612308, 2023). "Studies have reported that circRNA circ_104718, circRNA circ_CDR1AS, and circRNA circ_RHOT1 play a cancerigenic role in HCC, but circRNA circ_5692 and circRNA circ_TRIM33-12 exert anti-tumor role in HCC." (PMID 33407443, 2021).
tumor (continued). "KAT6A directly binds to and acetylates SMAD3 at K20 and K117, which promotes SMAD3 association with oncogenic chromatin modifier TRIM24 and disrupts its interaction with tumor suppressor TRIM33." (PMID 34392614, 2021). "We found that the expression levels of TRIM33 and E-cadherin in tumor tissues in the TRIM33 overexpression group were significantly higher than those in the control group." (PMID 32908919, 2020). "The expression of N-cadherin and vimentin in the tumor tissue in the control group were significantly higher than that in the TRIM33 overexpression group." (PMID 32908919, 2020). "TRIM33 overexpression reduced the expression levels of β-catenin, cyclin D1, and c-myc, and inhibited tumor growth in ccRCC cells in vivo." (PMID 32908919, 2020). "We found that the tumor volume and weight in the TRIM33 overexpression group were significantly lower than those in the control group." (PMID 32908919, 2020). "TRIM33 expression levels were correlated with clinical characteristics, including tumor size and Furman's grade." (PMID 32908919, 2020). "In contrast to the other TIF1 family members, TRIM33 has predominantly been identified as a tumour suppressor." (PMID 32731534, 2020). "While TRIM33 is largely considered to exhibit tumour suppressor activity, it is also reported to act as oncogene depending on the cell type involved." (PMID 29110249, 2018). "Xue et al24 showed that TRIM33 as a tumour suppressor that can abrogate tumour cell proliferation and tumorigenesis by degrading nuclear β‐catenin." (PMID 30079558, 2018). "Recent studies have found that TRIM33 abolishes tumour cell proliferation and tumorigenesis by degrading nuclear β-catenin via ubiquitination." (PMID 26624618, 2015). "We determined that TRIM33 drives aerobic glycolysis to promote tumor growth in vivo and in vitro." (PMID 39389957, 2024). "Our data showed that deletion of TRIM33 inhibited tumor growth in vivo." (PMID 39389957, 2024). "TRIM33 inhibits tumor cell proliferation and tumorigenesis by degrading nuclear β-catenin." (PMID 39389957, 2024). "In summary, these data support a tumor-promoting role of TRIM33 in ESCC." (PMID 39389957, 2024). "Compared to other TIF1 family members, TRIM33 mainly plays a tumor suppressor role." (PMID 37573347, 2023). "Furthermore, it was found that the combination of the expression of TRIM33 and the patient's tumor grade correlated with the prognosis of the patient (P < 0.0001)." (PMID 32908919, 2020). "A xenograft model was used to explore the effect of TRIM33 on tumor growth." (PMID 32908919, 2020). "However, the function of TRIM33 in tumors is complex; it can act as both a tumor suppressor or tumor promoter." (PMID 32908919, 2020). "Trim33 was found to act as a tumour suppressor in the pancreas of mice and humans." (PMID 26624618, 2015). "Importantly, the group suggested that TRIM33 may act as a tumor suppressor in GBM since its downregulation and subsequent Wnt pathway constant activation, promoting tumorigenesis in vivo and GBM cell proliferation in vitro." (PMID 36139694, 2022). "However, whether TRIM33 can affect tumor progression through the Wnt/β-catenin pathway in ccRCC is still unknown." (PMID 32908919, 2020). "Therefore, we speculated that the possibility of circRNA-derived TRIM33 acts as a tumor suppressor in HCC cells." (PMID 31153371, 2019). "Results of subcutaneous xenograft models demonstrated that TRIM33 knockdown promoted tumor growth, suggesting that TRIM33 inhibited TGF-β signaling to exert its tumor-suppressive role." (PMID 39768197, 2024).
tumor (continued). "In vivo and in vitro experiments have revealed that TRIM33 promotes the proliferation of ESCC cells, inhibits cell death, promotes tumor growth in nude mice, and plays a carcinogenic role in the occurrence and development of ESCC." (PMID 39389957, 2024). "Establishment of native tumor cell lines with other RET-fusions, including TRIM33-RET, CLIP1-RET, and ERC1-RET, is also warranted." (PMID 29088743, 2017). "The quantitative results showed that the expression of TRIM33 in ESCC was higher than that in normal esophageal tissues, and the staining site was mainly in the nucleus, which may be related to the tumor grade (Stage IV > Stage III ≈ Stage II > Stage I)." (PMID 39389957, 2024). "Because OC is primarily a tumor of epithelial origin, the expression of TRIM proteins was analyzed in epithelial cells, and the eight most highly expressed genes (TRIM28, TRIM27, TRIM33, TRIM38, TRIM47, TRIM56, TRIM8, and TRIM24) were determined." (PMID 38881325, 2024). "It was observed that the expression of TRIM33 in tumor tissue was significantly lower than that in the normal tissue (P = 7.708e‐19)." (PMID 32908919, 2020). "In the absence of TRIM33, SAC and post-mitotic checkpoints are attenuated enabling the accumulation of chromosomal abnormalities and increased tumour aggressiveness." (PMID 38627415, 2024). "TRIM33, unlike other TIF1 family members, has predominantly been identified as a tumor suppressor." (PMID 39160596, 2024).
infection (7 papers, 2019 to 2025). The state of being infected such as from the introduction of a foreign agent such as serum, vaccine, antigenic substance or organism. "Next, we established HeLa stable cells expressing TRIM8, TRIM25, TRIM26, TRIM32, and TRIM33 to evaluate their effects on VEEV-TC83-GFP infection." (PMID 39527628, 2024). "On the contrary, overexpression of the TRIM33 cDNA significantly decreased infection with this molecular clone (j for luciferase activity and levels of TRIM33 in the transfected cells, respectively)." (PMID 30804369, 2019). "Incoming HIV-1 IN degradation in the early hours after infection was markedly reduced in cells expressing the TRIM33 shRNA." (PMID 30804369, 2019). "We wanted to assess the role of TRIM33 in regulating degradation of IN carried by HIV-1 during infection." (PMID 30804369, 2019). "Forty-eight hours after infection of cells in which TRIM33 had been silenced, luciferase activity and, more markedly, the levels of integrated HIV-1 DNA were elevated, while those of 2LTR circles markedly reduced." (PMID 30804369, 2019). "First, we assessed efficiency of single-round infection of HeLa cells that had been depleted of TRIM33, with a VSV-G-pseudotyped HIV-1 vector carrying the luciferase gene under the control of the HIV-1 LTR (clone NL4-3.Luc.R-E-)." (PMID 30804369, 2019). "TRIM33 has been reported to restrict infection of multiple viruses by a variety of mechanisms." (PMID 37410772, 2023). "Together the results suggest that the interaction of BZLF1 with TRIM33 and TRIM24 in the context of lytic infection triggers phosphorylation and SUMOylation of TRIM33, as well as disruption of the TRIM complex, resulting in destabilization of TRIM24 and TRIM33." (PMID 37410772, 2023). "Infection was significantly increased in cells which stably expressed the anti-TRIM33 shRNA." (PMID 30804369, 2019). "We also show that TRIM33 expression, a negative regulator of host innate immune response, significantly promoted VEEV-TC83 infection." (PMID 38895352, 2024). "TRIM28 and TRIM33 are known to form a trimeric complex with TRIM24, which itself was found (above) to reduce in abundance in lytic infection." (PMID 37410772, 2023). "Knockout of either TRIM24 or TRIM33 significantly increased EBV genome amplification, with TRIM33 having the larger effect, likely because TRIM24 levels would already be low at this point in infection." (PMID 37410772, 2023). "In multiple-round infection experiments with HIV-1 BRU, knockdown of TRIM33 also increased IN level and promoted infection, while TRIM33 overexpression in KD cells impaired infection." (PMID 36293197, 2022). "In our study, we discovered that TRIM33 exhibited an up-regulation trend, which suggested that it might have played a similar role in the ARV infection process in ducks." (PMID 39973927, 2025). "In single-round infection experiments with VSV-G pseudotyped vector carrying luciferase reporter, TRIM33 knockdown promoted infection: the luciferase signal and the number of integrated DNA increased, while the number of 2-LTR circles, a sign of non-productive integration, decreased." (PMID 36293197, 2022). "Next, we transduced SupT1 T cells expressing shRNA #4 or shRNA #5 against TRIM33 and, after 6 day-puromycin selection, we infected these cells with wt HIV-1BRU; infection was monitored over a course of 12 days by measuring the amounts p24 viral protein in the cell culture supernatant." (PMID 30804369, 2019).
bacterial infection (1 paper, 2017). "In conclusion, our study reveals new important functions of TRIM33 in macrophage production and activation by LPS and links the TRIM33/PU.1 association to transcriptional changes that occur during the end of macrophage response to bacterial infection." (PMID 27974684, 2017).